RAMP1 (receptor activity modifying protein 1)
Diseases named in the same sentence as RAMP1 in open-access papers (continued):
Sharing a sentence is not in itself a finding about the gene and the disease.
cancer (14 papers, 2017 to 2025). A tumor composed of atypical neoplastic, often pleomorphic cells that invade other tissues. "The altered expression of RAMP1 has shown significant associations with cancer prognosis." (PMID 37796823, 2023). "In this study, the ARGs signature consisted of four genes (RAMP1, FOXL1, SLCO1B3, and F2RL2) that have previously been documented to be closely linked with cancer." (PMID 40165896, 2025). "Others have identified RAMP1 expression as a prognostic factor that is related to immune infiltration for some cancers." (PMID 39201643, 2024). "The level of immune cell infiltration in pan-cancer seemed to differ based on RAMP1 gene expression." (PMID 37796823, 2023). "Single-cell RNA-sequencing is used to identify cell types in the cancer microenvironment expressing the CGRP receptor components, receptor activity modifying protein 1 Ramp1 and calcitonin receptor like receptor (CLR, encoded by Calcrl)." (PMID 37443709, 2023). "RAMP1 is increasingly acknowledged to have a crucial role in the progression of non-neoplastic disorders in addition to the genesis and progression of cancer." (PMID 37796823, 2023). "After 2 days, 6 DEG were related to cancer such as Adcyap1, Ramp1, and Trpc3 which were down-regulated." (PMID 29950665, 2018). "Rather studies have focused on the angiogenic role of the CGRP/RAMP1/CALCRL complex instead its direct effects on cancer cells." (PMID 30598641, 2018). "Increased RAMP1 expression was strongly associated with the upregulation of lymphocyte activation gene 3 (LAG3), vascular endothelial growth factor B (VEGFB), and cytotoxic T-lymphocyte-associated protein 4 (CTLA-4) across multiple cancer types." (PMID 37796823, 2023). "RAMP1 has been found to be a cancer-promoting gene in many studies." (PMID 34733840, 2021). "Furthermore, studies suggest RAMP1 as a biomarker for tumorigenesis, impacting the MAP2KI (MEK1) signaling pathway (mitogen-activated protein kinase signaling pathway 2) and its association with neuronal nociceptors and cancer disease progression." (PMID 41234433, 2025). "RAMP1 functions in cancer cells may extend beyond signaling with CALCRL." (PMID 37443709, 2023). "There is a large literature about the presence of these receptors (NK1R, NK2R, RAMP1, and CALCRL) in different types of cancer cells." (PMID 30598641, 2018). "The presence of these receptors (NK1R, NK2R, RAMP1, and CALCRL) and the pro-tumorigenic effects of their activating NPs have been demonstrated in a piecemeal fashion across several types of cancer cell lines over the past two decades." (PMID 30598641, 2018). "As expected, we demonstrate the presence of these receptors (NK1R, NK2R, RAMP1, and CALCRL) in MDA-MD-231LUC+ cancer cells." (PMID 30598641, 2018). "Expression of RAMP1 and CALCRL in oral precancer and cancer cell lines was confirmed with qRT-PCR." (PMID 37443709, 2023). "Moreover, the relative abundance of human RAMP1- and CALCRL-expressing cells is maintained in the human cancer cells in the orthotopic xenografts." (PMID 37443709, 2023).
infection (2 papers, 2022). The state of being infected such as from the introduction of a foreign agent such as serum, vaccine, antigenic substance or organism. "In vitro, RAMP1 was overexpressed in MSF cell lines by infection with Tet-On-Flag-RAMP1 lentivirus and doxycycline (DOX) induction." (PMID 35413847, 2022). "Additionally, Western blot and qPCR analyses were performed to assess infection success, revealing that RAMP1 protein expression and mRNA transcription in the OE group were significantly higher than those in the VEC group." (PMID 35413847, 2022).
RAMP1 also shares sentences with these, for which no sentence is quoted: head and neck squamous cell carcinoma (2 papers); heart failure (2); Knee Osteoarthritis (2); uterine fibroids (2); acute myeloid leukemia (1); allergic disease (1); blood pressure (1); cardiovascular disease (1); colorectal cancer (1); concussion (1); endotoxemia (1); fibrosis (1); insomnia (1); liver fibrosis (1); lung fibrosis (1); migraine with aura (1); osteoarthritis (1); pancreatic adenocarcinoma (1); pancreatic cancer (1); periodontitis (1); prostate adenocarcinoma (1); pulmonary edema (1); Sepsis (1).